MELK (maternal embryonic leucine zipper kinase)
Diseases named in the same sentence as MELK in open-access papers (continued):
Sharing a sentence is not in itself a finding about the gene and the disease.
breast carcinoma (continued). "Moreover, a direct correlation between high MELK expression and malignancy grade has been reported in melanoma, breast cancer and brain tumors." (PMID 24167714, 2013). "For instance, MELK is required in cells that initiate mammary tumors." (PMID 24185907, 2013). "To assess a possible role of MELK in mammary carcinogenesis, we knocked down the expression of endogenous MELK in the breast cancer cell lines T47D and MCF7, in which MELK was overexpressed at a high level, by means of the mammalian vector-based RNAi technique." (PMID 17280616, 2007). "After comparing the expression profiles of these breast cancers with those of various normal human tissues, we focused on a gene termed maternal embryonic leucine zipper kinase (MELK) that was significantly overexpressed in the great majority of breast cancer cases examined." (PMID 17280616, 2007). "The kinase activity of MELK could be a promising molecular target for development of therapy for patients with breast cancers." (PMID 17280616, 2007). "To assess whether MELK has a role in mammary carcinogenesis, we knocked down the expression of endogenous MELK in breast cancer cell lines using mammalian vector-based RNA interference." (PMID 17280616, 2007). "Thus, to investigate the biological significance of MELK in breast cancer cells, we searched for a possible substrate(s) of MELK by means of in vitro pull-down assays with recombinant wild-type MELK (WT-MELK) and kinase-dead MELK (D150A-MELK)." (PMID 17280616, 2007). "The data suggest that CN changes of the gene may regulate MELK expression in breast cancer." (PMID 35749404, 2022). "As MELK expression has been suggested to have a positive correlation to histologic grade in human astrocytes and breast tumors, it may represent a novel prognostic marker to identify patients who have more aggressive breast cancer." (PMID 35749404, 2022). "Overall, the results demonstrated that the constitutive activation of PCDHB17P/miR-145-3p/MELK/NF-κB feedback loop promotes the metastasis and angiogenesis of breast cancer, suggesting that this lncRNA might be a promising prognostic biomarker and therapeutic target for breast cancer." (PMID 34350110, 2021). "Finally, MELK is known to increase DNA damage tolerance in breast cancer cells." (PMID 33431809, 2021). "Therefore, miR-145-3p suppressed MELK expression in breast cancer cells." (PMID 34350110, 2021). "Our study revealed a PCDHB17P/miR-145-3p/MELK/NF-kB feedback loop network in breast cancer metastasis and angiogenesis, which gives new insights into how PCDHB17P facilitates the development of breast cancer and might provide new targets for breast cancer treatment." (PMID 34350110, 2021). "In addition, high MELK expression level is related to poor prognosis in breast cancer patients." (PMID 32391256, 2020). "Moreover, six hub genes were selected and validated in clinical sample for further analysis owing to the high degree of connectivity, including CDK1, CCNA2, TOP2A, CCNB1, KIF11, and MELK, and they were all correlated to worse overall survival (OS) in breast cancer." (PMID 31428132, 2019). "The median expression of MELK was apparently lower in the three patients showing the deletion but it was not statistically significant (p > 0.05) suggesting that the region may be involved in breast cancer but the gene identity is uncertain." (PMID 31294536, 2019). "Unlike CCNB1, CCNA2, and CDK1, currently, the remaining genes (TOP2A, KIF11, and MELK) are not found to be associated with cell cycle; their dysfunctions might still affect the progression and prognosis of breast cancer." (PMID 31428132, 2019).
breast carcinoma (continued). "In addition to HTH-01-091, which exhibits substantially improved kinome selectivity in comparison with OTSSP167, we included MRT199665, NVS-MELK8a and MELK-T1 when we surveyed the proliferative response of a panel of breast cancer cell lines to MELK inhibition." (PMID 28926338, 2017). "To further examine whether MELK is required for the maintenance of established tumors, we administered doxycycline to mice bearing xenograft tumors derived from basal-like or luminal breast cancer cells." (PMID 24844244, 2014). "We performed experiments with cell lines representing various breast cancer subtypes to test our hypothesis that paclitaxel acts synergistically with doxorubicin via suppression of MELK, which in turn attenuates MYBL2 gene expression, known to be advantageous for chemotherapy response." (PMID 24349128, 2013). "Furthermore, to verify the molecular mechanism of this MELK-specific inhibitor, we demonstrate identification of new substrates of MELK and inhibitory effect of the compound on activities of these molecules in breast cancer cells." (PMID 23283305, 2012). "Boxplot analyses revealed that MELK, BIRC5, and CEACAM6 were significantly overexpressed in HR+/HER2– breast cancer tissues compared to normal breast tissues in the TCGA cohort, whereas RARRES1 expression was markedly reduced in tumor tissues (p < 0.001)." (PMID 40936892, 2025). "In silico molecular docking demonstrated strong binding affinities between major triterpenoid compounds and key breast cancer-related proteins, including HPA, MELK, CK2α, and NUDT5." (PMID 41237100, 2025). "Breast carcinoma is closely related to some gene products such as Helix Pomatia Agglutinin (HPA), Maternal Embryonic Leucine Zipper Kinase (MELK), Human Protein Kinase 2 alpha (CK2a), and NUDIX hydrolase 5 (NUDT5)." (PMID 41237100, 2025). "Recently, several studies have investigated the prognostic value of various genes in breast cancer, including NUSAP1, maternal embryonic leucine zipper kinase (MELK), and CDK1." (PMID 38084295, 2023). "The usage of bioinformatics tolls resulted in the identification of AURKA, AURKB, TTK, MELK and KIF20A as top 5 hub genes involved in breast cancer occurrence and progression." (PMID 37231064, 2023). "GEPIA analysis disclosed that breast cancer patients have significantly higher expression of AURKA (4.0 vs. 1.5), AURKB (4 vs. 1), TTK (2.5 vs. 0.5), MELK (3.0 vs. 0.5), KIF20A (3.5 vs. 0.5) genes compared to healthy people." (PMID 37231064, 2023). "We evaluated copy number alterations (CNA), DNA methylation, histone modifications, and MELK expression using publicly available databases, as well as conducting FISH, RNA-Seq, qRT-PCR, and IHC assays in breast cancer cell lines and tumors tissues." (PMID 35749404, 2022). "What’s more, the expression of MELK and PCDHB17P were positively correlated in Breast cancer tissues." (PMID 34350110, 2021). "Four hub genes, namely TOP2A (p=0.036), MELK (p=0.021), PBK (p=0.043), and RRM2 (p=0.012), were upregulated during breast cancer progression from normal tissue to DCIS and downregulated during disease progression from DCIS to IDC." (PMID 34094915, 2021). "In this review, we introduce three promising molecular targets, MELK, TOPK, and BIG3, that are specifically overexpressed in many cancers, including breast cancer." (PMID 34285339, 2021). "Supporting this data, MELK expression levels correlate with FOXM1 RNA expression levels, as well as with the FOXM1-regulated gene, Aurora kinase B (AURKB), in TCGA breast cancer dataset." (PMID 31909186, 2020). "MELK-expressing cells enriched from mammary tumors of MMTV-Wnt1/MELK-GFP mice have higher tumor-initiating potential both in vitro and in vivo, which is reversed upon MELK-targeting shRNA knockdown." (PMID 28926338, 2017). "Expression levels of only two genes (MELK, PLK1) gave positive Beta coefficients with breast cancer recurrence and mortality, with HRs between 1.20 and 1.25." (PMID 23819905, 2013).
breast carcinoma (continued). "Furthermore, our research has shown that MELK, NUSAP1, and CDK1 are crucial hub genes that are overexpressed in breast cancer and have potential roles as biomarkers." (PMID 38084295, 2023). "MELK (maternal embryonic leucine zipper kinase), a member of the Snf1/AMPK family of kinases, is overexpressed in various cancers, including breast cancer, and has been shown to be involved in CSC maintenance, malignant transformation, and cancer cell proliferation." (PMID 37377604, 2023). "Moreover, some genes, such as TTK and MELK, were repeatedly observed in various PAM50 subtypes of primary mammary carcinoma and even in bone-metastatic and skin-metastatic breast cancer." (PMID 37231064, 2023). "To date, there has not been a clinical trial of a MELKi in melanoma; yet, there is an ongoing phase-1 trial of MELKi in advanced breast cancer and triple-negative breast cancer (NCT02926690), suggesting the prognostic and potentially therapeutic relevance of MELK in tumor progression." (PMID 36741706, 2022). "The molecular mechanism of MELK dysregulation has not been determined in aggressive forms of breast cancer, such as triple negative breast cancer (TNBC)." (PMID 35749404, 2022). "Notably, through gene expression profiling analyses, we and others have reported that MELK is markedly upregulated in TNBC and basal-like breast cancer." (PMID 34285339, 2021). "The expression of MELK was also upregulated in other human malignant tumors such as hepatocellular carcinoma (HCC), gastric cancer (GC), neuroblastoma and breast cancer." (PMID 32047721, 2020). "One of these kinases, MELK, is highly expressed in TNBC tumors compared with normal breast and non-TNBC breast cancers, and the elevation of MELK expression occurs in early-stage breast cancers." (PMID 31909186, 2020). "Functionally, the ablation of MELK selectively inhibited the proliferation of basal-like breast cancer, but not type of luminal breast cancer cells both in vitro and in vivo." (PMID 31428132, 2019). "Interestingly, the analysis of breast cancer datasets revealed that the expression of PICH correlates with that of mitosis-related genes, such as KIF4A, CEP55, MKI67, MELK, BUB1, CENPA, and AURKB." (PMID 31160555, 2019). "Surprisingly, our results indicate that neither chemical inhibition nor genetic manipulation of MELK in breast cancer cell lines inhibited cell growth in vitro." (PMID 28926338, 2017). "In addition, MELK was successfully targeted by OTSSP167 compound and demonstrated a suppression of mammosphere formation in breast cancer cells and growth suppression of xenograft studied in multiple cancer types in mice." (PMID 26474389, 2015). "Ablation of MELK selectively impairs proliferation of basal-like, but not luminal breast cancer cells both in vitro and in vivo." (PMID 24844244, 2014). "To complement our RNAi-mediated MELK knockdown studies, we used a recently developed chemical inhibitor of MELK, OTSSP167, to evaluate the functional dependency on MELK by basal and luminal breast cancer cells." (PMID 24844244, 2014). "Even more striking is the finding that only basal-like, but not luminal breast cancer cells, depend on MELK for proliferation." (PMID 24844244, 2014). "In a comprehensive analysis of databases with multiple cohorts of breast cancer, we find MELK to be highly overexpressed in breast cancer lacking the expression of ER/PR, including basal-like breast cancer." (PMID 24844244, 2014). "To determine if the pharmacological inhibition of MELK would recapitulate the effect of MELK knockdown in xenografts, we administered OTSSP167 or vehicle control to mice that have tumors derived from basal or luminal breast cancer cell lines." (PMID 24844244, 2014).
breast carcinoma (continued). "We identified maternal embryonic leucine zipper kinase (MELK), that is a member of the AMPK serine/threonine kinase family and is involved in the mammalian embryonic development, to be a promising drug target molecule for breast cancer." (PMID 23283305, 2012). "The mechanisms how cancer cells acquired these abilities are not yet understood, but recent studies indicated that MELK is one of the marker molecules to characterize cancer stem cells in tumor, such as breast cancer and glioblastoma." (PMID 23283305, 2012). "Thus, we speculated that Narciclasine and Bruceine D could inhibit MCF7 cell proliferation through targeting MELK, CDK4, and MYC to regulate cell cycle in breast cancer." (PMID 38215156, 2024). "To test this hypothesis, we first assessed MELK expression in 23 human breast cancer cell lines, of which 16 were TNBC and seven were non-TNBC." (PMID 37377604, 2023). "Furthermore, in a univariate analysis, patients with breast cancer with tumors expressing high mRNA levels of MELK had significantly reduced PFS, DMFS, and OS compared with patients with tumors expressing low levels of MELK." (PMID 37377604, 2023). "However, MELK amplification or expression has not been evaluated as a prognostic marker to identify patients with aggressive breast cancer such as triple negative breast cancer (TNBC)." (PMID 35749404, 2022). "However, a few reports have demonstrated that MELK was not required for cell division in basal-like breast cancer, melanoma and colorectal cancer." (PMID 32047721, 2020). "Additionally, when breast cancer cells that do not produce MELK were exposed to the drug that is supposed to block MELK activity, the drug still stopped cell growth." (PMID 28337968, 2017). "We discover that MELK is essential in basal-like, but not in luminal breast cancer cells." (PMID 24844244, 2014). "Thus MELK overexpression appears to have a strong predictive value for breast cancer metastasis irrespective of tumor grade or treatment regimen." (PMID 24844244, 2014). "We performed statistical analysis of a large cohort of breast cancer for grade 1, 2 and 3 across all subtypes, respectively, and found that MELK is most highly expressed in BBC, suggesting that MELK expression is most pronounced in basal-like breast tumors with the same pathological grade." (PMID 24844244, 2014). "While MELK has a critical role in basal-like breast cancer, it is not clear whether this kinase is important for the proliferation of normal cells or tissue growth in vivo." (PMID 24844244, 2014). "Northern blot analyses on multiple human tissues and cancer cell lines demonstrated that MELK was overexpressed at a significantly high level in a great majority of breast cancers and cell lines, but was not expressed in normal vital organs (heart, liver, lung and kidney)." (PMID 17280616, 2007). "Interestingly, MELK could in turn increase the promoter activity and expression of PCDHB17P via NF-κB, thus forming a positive feedback loop that drives the metastasis and angiogenesis of breast cancer." (PMID 34350110, 2021). "Thus, in ERG-positive high-grade tumors (Gleason greater than 4+3), expressing a high level of LINC02418, the MELK inhibitor OTS167 could be a promising therapeutic opportunity, because it is already utilized in clinical trials for the treatment of breast cancer and onco-hematological pathologies." (PMID 33672425, 2021). "Our data showed that upregulation of MELK in BLBC may be in part driven by CN gains, rather than epigenetic modifications, indicating a potential for overexpression and CN gains of MELK to be developed as a diagnostic and prognostic marker to identify patients who have more aggressive breast cancer." (PMID 35749404, 2022).
breast carcinoma (continued). "In agreement with our findings from the breast cancer patient dataset, we found that 10 of 16 TNBC cell lines (62%), compared with two of eight non-TNBC cell lines (25%), expressed high mRNA levels of MELK, which positively correlated with MELK protein levels." (PMID 37377604, 2023). "Together, these data indicate that MELK is a normally non-essential kinase, but is critical for BBC and thus represents a promising selective therapeutic target for the most aggressive subtype of breast cancer." (PMID 24844244, 2014). "However, why MELK is selectively required for cell division in BBC cells, but not in other types of breast cancer or normal cells, remains an open question." (PMID 24844244, 2014). "Conversely, in vivo inhibition of MELK activity through the inhibitor OTSSP167 in breast cancer xenograft models revealed that inhibition of MELK activity reduced the growth of basal-like cell breast cancer xenografts, but not of luminal cell breast cancer xenografts." (PMID 34550356, 2021).